BRAF (B-Raf proto-oncogene, serine/threonine kinase)
Diseases named in the same sentence as BRAF in open-access papers (continued):
Sharing a sentence is not in itself a finding about the gene and the disease.
glioma (continued). "Since human BRAF mutations have been often detected in children, five glioma samples, classified as WHO grade I–V types, were collected from pediatric patients." (PMID 36763212, 2023). "BRAF V600 mutations have been identified in several adult glioma subtypes, including PXAs, gangliogliomas, anaplastic gangliogliomas, PAs, and, more rarely, adult HGGs (aHGGs) including GBM, with an overall incidence of 4%." (PMID 37124503, 2023). "Glioma samples tested by the brain subpanel had BRAF variants at 8% and IDH1/IDH2 variants at 12.5%." (PMID 37483495, 2023). "Desmoplastic infant astrocytomas/gliomas exhibit the p.V600K variant, while the BRAF p.V504_R506dup variant was reported in cases with PA." (PMID 37397394, 2023). "The rarity of BRAF mutations in glioma patients rises some issues related to financial investments and clinical trial design on patients with glioma." (PMID 36686797, 2022). "In pediatric low-grade glioma, patients harboring the BRAF V600E mutation exhibited poor clinical outcomes after chemotherapy and radiotherapy with a 10-year PFS rate of 27% and 60.2% for the BRAF V600E wild type." (PMID 35186740, 2022). "BRAF inhibitors are already in use in the treatment of BRAF mutated high and low grade gliomas LGGs." (PMID 35574540, 2022). "were able to identify several kinds of BRAF mutations occurring in glioma and belonging to all three classes of BRAF alterations." (PMID 36686797, 2022). "The recent discovery that most low-grade sporadic pediatric gliomas have BRAF mutations has focused efforts on understanding biology related to this biochemical pathway and its pathological activation." (PMID 36077798, 2022). "This case series describes clinical and radiological responses to BRAF-targeted therapy in BRAF V600E-mutated gliomas across multiple tumor grades and is only the second published report of response to targeted therapy in BRAF-mutated RDD." (PMID 36619621, 2022). "Despite the relatively low incidence of BRAF V600E mutations in high grade gliomas, mounting evidence has suggested that BRAF targeted therapy represents a promising treatment option for adults with BRAF mutated high grade gliomas or GBM." (PMID 36686797, 2022). "The response rate in BRAF V600E-mutant gliomas exceeds 30%, with associated clinical benefit and prolonged tumor control." (PMID 35267432, 2022). "The possible application of BRAF-targeted therapy in gliomas is continuously growing and there is preliminary evidence of prolonged disease control obtained by BRAF inhibitors in tumors harboring BRAF V600E mutation." (PMID 36686797, 2022). "Though thought to be generally mutually exclusive, it is unclear how patients with BRAFV600E gliomas harboring additional genetic alterations at the level of BRAF (mutations and/or fusions) respond to BRAFi." (PMID 36698391, 2022). "We investigated FFPE DNA from glioma tissue samples of 22 patients for BRAF V600 mutations by ddPCR." (PMID 35361262, 2022). "Preclinical studies using an orthotopic murine BRAF V600E mutated glioma model confirmed that BRAF V600E inhibitor monotherapy with dabrafenib inhibited MAPK signaling only transiently." (PMID 36686797, 2022). "Although BRAF mutation was observed in several glioma subtypes, it was rare in high grade gliomas including GBM." (PMID 35135556, 2022). "Multiple case reports and series have described therapeutic responses to BRAF-targeted therapy in BRAF V600E-mutated gliomas across all WHO tumor grades in both pediatric and adult populations, including some cases of complete tumor regression." (PMID 36619621, 2022). "Apart from BRAF mutations, in glioma, RAS/MAPK signaling can be activated by neurofibromatosis 1 (NF1) gene inactivating mutations or deletions." (PMID 35875139, 2022). "Class III mutations are rarer than class I and II ones (4-10% of BRAF mutation in glioma) and contrarily to the other classes are RAS-dependent." (PMID 36686797, 2022).
glioma (continued). "Further, resistance to BRAF inhibition was observed in V600E-mutated glioma cell lines with additional epidermal growth factor receptor (EGFR) amplification." (PMID 35158978, 2022). "We showed that in the younger adults, it is associated with good survival, and similarly, good survival with BRAF V600E mutated gliomas was shown in smaller series." (PMID 35558510, 2022). "BRAF became the focus of research recently since a large portion of human tumors carry oncogenic ‘driver’ mutations in the BRAF gene, with 11% of glioma cell lines harboring BRAF mutations." (PMID 35785151, 2022). "The BRAF (V600E) mutation is important in childhood CNS tumors, and a study showed that the autophagy inhibitor chloroquine reduced tumor viability in glioma cells with the BRAF (V600E) mutation." (PMID 36197606, 2022). "Patients with BRAF V600E‐mutant glioma and BRAF V600E‐mutated biliary tract cancer benefited from the dabrafenib plus trametinib based on the results of the phase II ROAR trial." (PMID 36254250, 2022). "The identification of BRAF p.V600E mutations in gliomas is nowadays of more importance regarding the development of BRAF-targeted inhibitors." (PMID 36158392, 2022). "To date, the only study carried out on glioma patients confirmed that the acquisition of alternative BRAF mutations is a strategy adopted by tumors to overcome BRAF inhibition." (PMID 36686797, 2022). "Studies using BRAF V600E mutated high-grade glioma cells and flank xenografts demonstrated that BRAF V600E inhibitor Vemurafenib did not eliminate all tumor cells equally." (PMID 36686797, 2022). "Our data indicated that in adult glioma patients with BRAF mutations, including both BRAFnon-V600E and BRAFV600E cohorts, glioblastoma multiform was the most common cancer type." (PMID 33980169, 2021). "In this study, we provide evidence of the technical development of a ddPCR assay for the detection of BRAF V600E mutations in the plasma of patients with glioma or brain metastasis." (PMID 33799709, 2021). "BRAF mutations have also been implicated in glioma tumorigenesis prompting investigation of the use of BRAF targeted therapies in glioma." (PMID 33799709, 2021). "A meta-analysis encompassing 1308 adults and paediatric gliomas from 11 studies revealed that children aged 0 to 16 years old with a BRAF V600E mutation have a favourable prognosis, with a hazard ratio of 0.51." (PMID 33557011, 2021). "Vemurafenib is a competitive small-molecule BRAF V600E inhibitor that can act on BRAF V600E mutations in low-grade gliomas." (PMID 34712139, 2021). "Dabrafenib, one of those agents, is expected to improve clinical outcomes with few adverse events and good tolerance in patients with BRAF-mutated gliomas." (PMID 33673070, 2021). "Due to the high prevalence of the BRAF V600E mutation in paediatric gliomas, this case study provided a positive indication for Vemurafenib in the treatment of these tumours." (PMID 33557011, 2021). "In our cohort, P4 and P5 had gliomas positive for the BRAF V600E mutation with P4 having a PXA with MAF of 0.452% at the time of resection." (PMID 33799709, 2021). "In this study, the available data of patients with BRAFnon-V600E and BRAFV600E in the TCGA CNS/brain database were investigated to determine the possible mechanisms of BRAF gene mutations in adult glioma patients." (PMID 33980169, 2021). "FGFR1 and BRAF mutations are typical hallmarks of low grade glioma, such as pilocytic astrocytoma, ganglioglioma, or dysembryoplastic neuroepithelial tumor." (PMID 33433639, 2021). "In this paper, we focus on the technical development of the BRAF V600E hotspot mutations in gliomas and CNS metastases." (PMID 33799709, 2021). "V600E is the most frequent mutation in the BRAF gene described in gliomas, occurring in about 5% of adults." (PMID 34359651, 2021). "Our results showed the possible synergy of CDKN2A and CDKN2B HDs with BRAF mutations, especially in adult glioma patients with BRAFV600E and BRAFnon-V600E." (PMID 33980169, 2021).
glioma (continued). "Studies have also shown that glioblastomas and other types of gliomas tend to have low frequencies of BRAF mutations." (PMID 33237934, 2020). "Targeting the MAPK pathway has also been of interest to researchers, as a small proportion of glioblastoma and glioma subtypes harbor BRAF V600E mutations." (PMID 33396284, 2020). "The combination strategy, with the BRAF inhibitor dabrafenib plus MEK inhibitor trametinib, demonstrated promising efficacy in patients with recurrent or refractory BRAF exon 15 p.V600E-mutated high-grade and low-grade gliomas." (PMID 33260892, 2020). "The OS of histological grade II/III glioma patients with the BRAF V600E mutation was significantly higher than that of patients without the mutation (P = 0.032)." (PMID 32228694, 2020). "Univariate and multivariate analysis: characteristics associated with BRAFAMP and BRAF mutation in gliomas." (PMID 33489866, 2020). "One phase II trial studied selumetinib in recurrent or refractory BRAF-aberrant or NF1 associated low-grade gliomas." (PMID 33042847, 2020). "Well-demarcated gliomas identified by mutations in oncogene BRAF are usually classified as grade I tumors histologically." (PMID 32642706, 2020). "The BRAFAMP and IDH1/2WT genotype was found to be an independent predictive factor for glioma with BRAF mutation and BRAFAMP using Cox proportional hazard regression analysis (HR = 0.138, P = 0.018)." (PMID 33489866, 2020). "The other primary neurosphere model was derived from supratentorial glioma tissue harboring BRAF V600E mutation (patient 99)." (PMID 32616776, 2020). "The results of Cox proportional hazard regression analysis show that BRAFAMP and IDH1/2WT genotype was an independent predictive factor for glioma with BRAF mutation and BRAFAMP." (PMID 33489866, 2020). "The BRAFV600E mutation in which the thymine at nucleotide 1799 is substituted by adenine results in the substitution of valine with glutamic acid at amino acid 600; this is the most common BRAF mutation in glioma." (PMID 33489866, 2020). "Other previous reports have indicated sensitivity to BRAF inhibitor alone for gliomas with BRAF V600E mutations, the majority being gangliogliomas in children and PXAs in adults." (PMID 31345255, 2019). "Cell proliferation assays with BRAF-inhibitors confirmed the selective activity against BRAFV600E-mutated glioma cells, as already reported by previous preclinical studies and case series." (PMID 31391125, 2019). "Despite a relatively low incidence in adults, the potential for targeted therapy makes BRAF V600 mutations in recurrent gliomas significant as prognosis is poor and treatment options are very limited." (PMID 31466300, 2019). "Thirty-nine gliomas with BRAF mutations were identified in cBioPortal, of which 17 (44%) had V600E mutations, eight had other known activating mutations (20%), and five had fusions conferring kinase activity (13%)." (PMID 31466300, 2019). "More recent reports have documented successful treatment of high-grade gliomas with BRAF V600E mutations using a combination of dabrafenib and trametinib." (PMID 31345255, 2019). "Shortly after the identification of BRAF as an important oncogene in cancer in 2002, the first BRAF mutations in glioma have been described in 2004." (PMID 31181803, 2019). "While V600E is the most common mutation in BRAF, other mutations are being identified in glioma due to increasing use of clinical NGS." (PMID 31466300, 2019). "BRAF V600E mutations are rarely found in adult gliomas with only 1% to 2 % mutated samples in glioblastomas and 2% to 5% in low grade adult gliomas." (PMID 31181803, 2019). "Here, we summarize the mutations in BRAF described to date in glioma and provide an overview of their functional implications for tumor biology and treatment with targeted drugs." (PMID 31466300, 2019).
glioma (continued). "In a basket study of vemurafenib in adults with BRAF V600E-mutated gliomas, the response rate of adults with PXA was high (43%; 3/7) and similar to pediatric patients, but the response rate in GBM and anaplastic astrocytoma was much lower at 9% (1/11)." (PMID 31466300, 2019). "While clinical trials are still ongoing, there is preliminary evidence for a range of positive response rates in different types of glioma with BRAF V600E mutations." (PMID 31466300, 2019). "BRAF is only amplified/mutated in 2% of TCGA patients, but it is expressed at medium to high levels in all glioma specimens in HPA." (PMID 31500569, 2019). "Using cBioPortal.org, multiple patient cohorts were queried for glioma with mutations in BRAF (MSK-IMPACT Clinical Sequencing Cohort and TCGA)." (PMID 31466300, 2019). "Given the paucity of treatments for primary brain tumors and the poor prognosis associated with high-grade gliomas, BRAF mutations in glioma are of considerable interest." (PMID 31466300, 2019). "Similar to other cancers, the most common mutation in the BRAF gene in glioma is the c.1799T>A mutation." (PMID 31466300, 2019). "A mutation specific monoclonal antibody (clone VE1) for rapid immunohistochemical detection of the BRAF V600E mutation was developed and successfully applied and validated in central nervous system tumors." (PMID 31181803, 2019). "In this review the different central nervous system tumors harboring BRAF alterations are presented and the diagnostic significance, prognostic role, and therapeutic potential are discussed." (PMID 31181803, 2019). "UAI-201 is another BRAF targeting drug that was found to cause dose-dependent inhibition of glioma growth in cells with V600E mutation, including the KG-1-C line from glioma cells of a 13 year old boy." (PMID 30443293, 2018). "In contrast, KIAA1549:BRAF fusion variants are rare in these tumors, being observed only in low-grade glioneuronal (gangliogliomas) tumors (36%) and low-grade unclassifiable gliomas (17%)." (PMID 30279357, 2018). "The BRAF mutation V600E is critical for the pathogenesis of pediatric gliomas and specific inhibitors of the mutated protein, such as Vemurafenib, are available." (PMID 30488019, 2018). "Lastly, using homology-directed-repair, we also produce tumors carrying the homologous mutation to human BRAF V600E, frequently identified in a variety of tumors, including different types of gliomas." (PMID 29654229, 2018). "At variance with BRAF rearrangements, the role of BRAF V600E mutation in the glioma’s evolution and patient’s follow-up is far from being fully understood and some contradictory results are found in literature." (PMID 30558563, 2018). "As to the incidence rate of BRAF V600E mutation results corroborated previous data, showing that this mutation occurred in all spectra of glioma types, although being more frequent in gangliogliomas and diffuse astrocytomas." (PMID 30558563, 2018). "The activating BRAF V600E mutation is a common genetic alteration in low grade gliomas and glioneuronal tumors, and has been reported in SEGAs as well." (PMID 29221145, 2017). "A recent study demonstrated that a Braf codon 545 mutation (V545E, corresponding to the human BRAF V600E mutation) is a frequent early event in the development of ENU-induced rat gliomas." (PMID 28074274, 2017). "Although the prevalence of BRAF mutations in low grade gliomas is relatively low, BRAFV600E mutations have been consistently reported as genetic driver in gangliogliomas (18-56%), and have been associated with mTORC1 activation." (PMID 29221145, 2017). "Recent study also reported the activating mutation BRAF-V600E identified a distinct clinical subgroup of pediatric high grade gliomas." (PMID 26452024, 2016). "The effectiveness of this method was explored using IDH1/2 and BRAF mutations in clinical glioma samples." (PMID 27529619, 2016).
glioma (continued). "The potential prognostic value of BRAF-V600E mutation was also recently reported in pediatric high-grade gliomas." (PMID 26452024, 2016). "Mistry and colleagues described a series of pediatric secondary high-grade gliomas harboring BRAF mutation and CDKN2A deletion, showing longer latency to transformation from low-grade lesion and better clinical outcome." (PMID 26452024, 2016). "BRAF-V600E mutation was frequently identified in pediatric low-grade gliomas including pleomorphic xanthoastrocytoma, ganglioglioma and extra-cerebellar pilocytic astrocytoma." (PMID 26452024, 2016). "Dr Mark Kieran (Dana Farber Cancer Institute, USA) presented preliminary data of dabrafenib, a BRAF inhibitor, for the <10% of paediatric glioma patients with a BRAF V600 mutation." (PMID 28105074, 2016). "Further mutations have been found in the BRAF gene in gliomas including a 3bp insertion at codon 598 which mimics the V600E mutation." (PMID 25785246, 2015). "We set out to determine if the BRAF-KD is sufficient to induce gliomas alone or in combination with Ink4a/Arf loss." (PMID 25821557, 2015). "Mutational activation of BRAF (BRAFV600E) occurs in pediatric glioma and drives aberrant MAPK signaling independently of upstream cues." (PMID 26023796, 2015). "Our findings demonstrate that the BRAF-KD can cooperate with Ink4a/Arf loss to drive the development of gliomas and suggest that glioma development is determined by the level of MAPK signaling." (PMID 25821557, 2015). "This review describes the molecular biology of BRAF in the context of pediatric low-grade gliomas, the role of BRAF as a diagnostic marker, the prognostic implications of BRAF, and evidence for therapeutic targeting of BRAF." (PMID 25785246, 2015). "Here, we set out to determine if the BRAF-KD is sufficient to induce gliomas in vivo alone or in combination with Ink4a/Arf loss." (PMID 25821557, 2015). "Patients with low-grade gliomas and the BRAF V600E mutation have poorer outcomes and a decreased progression-free survival." (PMID 25563358, 2014). "Here we describe the first known case of complete response in a BRAF V600E-mutated high-grade glioma to vemurafenib (BRAF inhibitor) therapy." (PMID 24725538, 2014). "For example, IDH1 and IDH2 mutations are associated with much better glioma patient prognosis, and the BRAF mutation was associated with more favorable acral lentiginous melanoma prognosis." (PMID 25332145, 2014). "In sporadic low-grade gliomas driven by KIAA1549:BRAF and familial low-grade gliomas associated with protein neurofibromin 1 (NF1), mTOR represents a central growth control target." (PMID 23717811, 2013). "In pediatric brain tumors, EGFR alterations are infrequent but our work and that of others suggests that activating BRAF mutations play a central role in both low and high grade glial tumors." (PMID 23592488, 2013). "This Phase I study will establish the safety and pharmacokinetic characteristics of vemurafenib in children with recurrent or refractory gliomas containing the BRAF V600E mutation." (PMID 23717811, 2013). "There continues to remain controversy about the prognostic significance of the BRAF V600E mutation in pediatric gliomas." (PMID 23717811, 2013). "While a more complete survey of other uncommon low-grade gliomas is still required, it appears likely that the high frequency of BRAF V600E mutations will be the hallmark of PXA and GG." (PMID 21479234, 2011). "Additionally, other gene mutations, for instance, BRAF variants have been implicated in enhancing epileptogenicity in gliomas while pathways, such as RAS/MAPK and PI3K/AKT/mTOR, play significant roles in both neuronal excitability and tumor growth." (PMID 40718831, 2025). "Clinically, gliomas with BRAF p.Val600Glu (V600E) mutations have shown responsiveness to molecularly targeted treatments, as demonstrated in trials for pediatric gliomas, and may be associated with a slightly better prognosis in certain contexts." (PMID 41473634, 2025).